OASL (2'-5'-oligoadenylate synthetase like)
Diseases named in the same sentence as OASL in open-access papers (continued):
Sharing a sentence is not in itself a finding about the gene and the disease.
cervical cancer (4 papers, 2016 to 2023). A primary or metastatic malignant neoplasm involving the cervix. "The high expressions of ISG15, IFI27, and OASL were also correlated with complete remission in patients with cervical cancer treated with cisplatin." (PMID 37174688, 2023). "A recent study showed that OASL expression is relatively high in HPV positive cervical cancer, and seemed to be related with resistance to cisplatin." (PMID 32849815, 2020). "This study also found that high expressions of ISG15, IFI27, and OASL were associated with complete remission in patients with cervical cancer treated with cisplatin but not in those without cisplatin-based therapy." (PMID 37174688, 2023). "Other studies have shown that OASL is closely related to the drug sensitivity of cervical cancer." (PMID 36162993, 2022). "Since KU55933 induced the expressions of ISG15, IFI27, and OASL in CDDP-R cancer cells, the effects of the three ISGs on the response to cisplatin therapy were examined in patients with cervical cancer from the TCGA cohort." (PMID 37174688, 2023). "Different expressions of OASL represent different drug-sensitivity to cisplatin in HPV + and HPV − cervical cancers." (PMID 36162993, 2022). "Although Gal-7 affects the specific cervical cancer networks in different ways, we identified a group of eight molecules that are regulated in both cell lines: CRYAB, TACSTD2, BCL-3, COX19, OASL, CDKN2A/p14ARF, NIBAN/FAM129A, and FST." (PMID 27558259, 2016).
systemic sclerosis (4 papers, 2015 to 2023). A chronic disorder, possibly autoimmune, marked by excessive production of collagen which results in hardening and thickening of body tissues. "Expression of OASL is upregulated in some diseases, including SLE, systemic sclerosis, and juvenile dermatomyositis." (PMID 34149799, 2021).
ZIKV infection (4 papers, 2018 to 2024). "Another protein interactor of ZIKV E was 2′,5′-Oligoadenylate synthetase-like (OASL), an interferon stimulated gene that has been shown to be anti-viral against hepatitis C virus and has also been implicated in the response to ZIKV infection in placentas." (PMID 32397571, 2020). "Generation of innate AVPs, including OAS1, OAS2, OASL, and MX1, in response to IL27 was found to be protective against Zika virus infection in human keratinocytes." (PMID 37310504, 2023).
co-infection (3 papers, 2020 to 2023). "At 96 h after infection, the transcription levels of OASL and Mx showed the same pattern as above; that is, co-infection with aHEV-YT downregulated the transcription levels of most of the immune-related factors detected in this study that were otherwise induced by FAdV-4 GY single infection." (PMID 37896849, 2023). "Finally,the mRNA levels of several cytokines were determined, and showed that the transcription of IFNB1, TNF, IL1B, and OASL was higher in the co-infection group than in the singly infected group, which may have been the consequence of increased PEDV replication." (PMID 37065133, 2023). "The transcription levels of MDA5, Mx, OASL, and IFN-α were significantly upregulated in LMH cells, whereas those of immune-related factors induced by FAdV-4 were downregulated upon FAdV-4 and aHEV co-infection." (PMID 37896849, 2023). "The co-infection allowed observation of multiple genes involved in the obstruction of the viral life cycle within the host such as MX1,MX2, OASL, OAS2, heat shock protein family A (Hsp70) member 8 (HSPA8), and radical S-adenosyl methionine domain containing 2 (RSAD2)." (PMID 33187194, 2020).
oral cancer (3 papers, 2022 to 2024). "In oral cancer, high expressions of ISG15, IFI27, and OASL were found to be associated with low ATM expression (mimicry of ATM inhibition), the activation of inflamed immune pathways, and elevated tumor-infiltrated scores of pDC, NK, and CD8+ T cells." (PMID 37174688, 2023). "The effect of ISG15/IFI27/OASL expression on the configurations of tumor-infiltrated lymphocytes in oral cancer was examined using the cell-type enrichment analysis algorithm xCell." (PMID 37174688, 2023). "The induction of ISG15, IFI27, and OASL expression by KU55933 was also observed in oral cancer cells CAL27 and derived CDDP-R cancer cells." (PMID 37174688, 2023). "In oral cancer, high expressions of ISG15, IFI27, and OASL were associated with low expressions of ATM, the activation of inflamed immune pathways, and increased tumor-infiltrating scores of CD8+ T, natural killer, and dendritic cells." (PMID 37174688, 2023). "Among these ISGs, the high expressions of ISG15, IFI27, and OASL were associated with low ATM expression, the activation of immune pathways, and high tumor-infiltrating scores of DCs, NK, and cytotoxic CD8+ T cells in oral cancer." (PMID 37174688, 2023). "Significantly, OASL|SPP1 was the most strongly and negatively correlated with the prognosis of oral cancer." (PMID 35804390, 2022).
pancreatic ductal adenocarcinoma (3 papers, 2022 to 2025). An infiltrating adenocarcinoma that arises from the epithelial cells of the pancreas. "In Badea Pancreas dataset, OASL was upregulated with a fold change of 1.820 in pancreatic ductal adenocarcinoma." (PMID 35719943, 2022).
psoriasis (3 papers, 2016 to 2025). An autoimmune condition characterized by red, well-delineated plaques with silvery scales that are usually on the extensor surfaces and scalp. "In another study based on the expression profile analysis of psoriasis vulgaris diffuse genes, OASL/OAS2/OAS3 were considered as novel hub genes associated with psoriasis." (PMID 40560938, 2025). "In summary, the study identified a series of characteristic genes (DEFB103A, IFI16, OAS3, OASL, SAMD9, STAT1, etc.)that are highly related to the occurrence, treatment of psoriasis." (PMID 40560938, 2025). "A total of 5 genes (DEFB103A, OAS3, OASL, SAMD9, STAT1) were co-identified as characteristic genes in psoriasis progression and treatment." (PMID 40560938, 2025). "IVL, OASL, and ISG15 were also the potential gene targets of the drugs for treating psoriasis in this study." (PMID 32669126, 2020). "In addition, 8 genes (DEFB103A, OASL, HERC6, ISG15, MKI67, MX1, MXD1, SCO2) were considered to have statistically significant differences in sensitivity of short-term treatment for psoriasis." (PMID 40560938, 2025). "Finally, PPI network analysis demonstrated that CXCL10 was the hub gene with the highest degree, and CXCR2, CXCL10, IVL, OASL, and ISG15 were the potential gene targets of the drugs for treating psoriasis." (PMID 32669126, 2020). "One can observe that the top psoriasis genes, including IFNg genes OASL, MX1; IL17-regulated CCL20 and IL19 are not different in the PPPP/PPP as compared with normal acral skin." (PMID 27152848, 2016). "Besides, some psoriasis-related genes such as SPRR genes, HSD11B1, GGH, CXCR2, IVL, OASL, ISG15, and CXCL10 may be important targets in psoriatic therapy." (PMID 32669126, 2020).
atherosclerosis (2 papers, 2020 to 2022). A disease characterized by the build-up of fatty material and calcium deposition in the arterial wall resulting in partial or complete occlusion of the arterial lumen. "Even though further insight into the phenotypes affected by OASL variants is needed, identifying and modulating OASL expression may represent a therapeutic strategy for atherosclerosis treatment." (PMID 36333342, 2022). "To determine whether OASL expression is associated with atherosclerosis, we measured OASL expression levels in atheroma tissue with or without plaques." (PMID 36333342, 2022). "In this study, we examined the role of mouse OASL1 and its human ortholog, OASL, in atherosclerosis." (PMID 36333342, 2022). "Similar to the results for human OASL, the expression of murine Oasl1 transcripts in the aorta of Apoe−/− mice with advanced atherosclerosis was altered in plaque-containing atherosclerotic aortas compared with those without plaques." (PMID 36333342, 2022). "Our results suggest that OASL functions as a homeostatic mediator in ECs through regulation of the miR-584-eNOS axis and may lead to new treatment strategies for atherosclerosis and other cardiovascular disorders mediated through endothelial dysfunction." (PMID 36333342, 2022). "Because murine endothelial OASL1-mediated atheroprotective effects are conserved in human OASL, controlling the OASL-miR-584-eNOS regulatory axis may represent an effective therapeutic strategy for treating human atherosclerosis and other vascular diseases mediated by endothelial dysfunction." (PMID 36333342, 2022). "Similarly, OASL-KD HUVECs promoted immune cell adhesion and enhanced inflammatory signaling including the ERK1/ERK2 cascade and the NF-κB signaling pathway, both of which are known to decrease eNOS expression and promote atherosclerosis progression." (PMID 36333342, 2022).
bladder urothelial carcinoma (2 papers, 2022 to 2024). "However, OASL’s overexpression indicates better overall survival for patients in bladder urothelial carcinoma (BLCA), and is associated with the infiltration levels of CD4+ T cells, CD8+ T cells, neutrophils, and dendritic cells." (PMID 39286258, 2024). "The genes co-expressed with OAS1, OAS2, OAS3, and OASL in Sanchez-Carbayo Bladder 2 dataset were identified using Oncomine in 48 normal samples, 81 filtrating bladder urothelial carcinoma tissues, and 28 superficial bladder cancer tissues." (PMID 36162993, 2022).
Dengue (2 papers, 2015 to 2023). "Expression of BISPR, OASL, and BST2 were upregulated during acute Dengue and Zika infection, similarly to what we observed in acute Chikungunya infection." (PMID 37922302, 2023). "When comparing controlled versus hemorrhagic dengue (GSE18090, unpublished data), we found that the individual expression of ISG15, OASL, OAS2 and TNFSF10 can be used to anticipate the complication status of dengue infection into a hemorrhagic outcome." (PMID 26302899, 2015).
glioma (2 papers, 2024 to 2025). A benign or malignant brain and spinal cord tumor that arises from glial cells (astrocytes, oligodendrocytes, ependymal cells). "Additionally, targeting upregulation of OASL may provide a novel strategy to enhance necrotic apoptosis in glioma cells after NDV infection." (PMID 40330823, 2025). "We identified five critical genes (HOXA2, CHI3L1, POSTN, OASL, and ZNF474) with substantial roles in the glioma context." (PMID 38473752, 2024).
HIV-1 infection (2 papers, 2019 to 2023). The type species of lentivirus and the etiologic agent of acquired immunodeficiency syndrome (AIDS). "Most interestingly, silencing of OAS1, OAS2, OAS3, or OASL markedly increased HIV-1 replication in human brain pericytes, providing the first evidence that the OAS family can regulate HIV-1 infection in human pericytes." (PMID 37209263, 2023). "Finally, no changes were detected in OASL protein levels after HIV-1 infection." (PMID 37209263, 2023).
leprosy (2 papers, 2018). Leprosy is a chronic infectious disease affecting primarily the skin and peripheral nervous system. "OASL was also shown to be upregulated in M. leprae–infected human macrophage cell lineages, primary monocytes, and skin lesion from patients with a disseminated form of leprosy; whereas OASL knock down was associated with decreased viability of M. leprae and upregulation of autophagy levels." (PMID 30143000, 2018).
rheumatoid arthritis (2 papers, 2015 to 2024). A chronic, systemic autoimmune disorder characterized by inflammation in the synovial membranes and articular surfaces. "OASL may also serve as a predictive biomarker for assessing rheumatoid arthritis (RA) patients’ response to tocilizumab." (PMID 39286258, 2024).
adenovirus infection (1 paper, 2023). "Of these, SOCS3, OASL, ISG15, and IFIT1 were found to be involved in the process of adenovirus infection and were thus regarded as candidate genes." (PMID 37017816, 2023). "Transcriptome sequencing showed that the expression levels of SOCS3, OASL, ISG15, and IFIT1 increased significantly over time, especially at 48 hpi (except SOCS3) and 72 hpi, suggesting that these genes might play an important role in adenovirus infection." (PMID 37017816, 2023).
Aicardi-Goutières syndrome (1 paper, 2021). "We next examined baseline gene expression (qPCR) of archetypal interferon stimulated genes (ISGs) IFI27, USP18, MX1, OASL, IRF7, and MX2, and those ISGs found highly expressed in PBMCs from the type 1 interferonopathy, Aicardi-Goutières syndrome (AGS) patients (IFI27, ISG15, IFI44L, and RSAD2)." (PMID 33746960, 2021).
arboviral diseases (1 paper, 2023). "Expression of BISPR, BST2, and OASL in other arboviral diseases." (PMID 37922302, 2023).
Arthritis (1 paper, 2020). Inflammation of a joint. "Moreover, active SLE patients with renal disorders and arthritis showed higher OAS2, OAS3, and OASL expression than patients without these symptoms." (PMID 32321151, 2020).
breast tumors (1 paper, 2024). "Taken together, these findings underscore the distinct expression patterns of OAS1, OAS2, OAS3, and OASL in breast tumors across a spectrum of immune and molecular subtypes." (PMID 39633486, 2024).
chlamydial infection (1 paper, 2022). "We note the significant upregulation of genes previously identified to respond to acute and persistent chlamydial infection, such as the antiviral protein OASL, in UTD24, TRP16, and TRP24." (PMID 36377897, 2022).
colorectal cancer (1 paper, 2024). A primary or metastatic malignant neoplasm that affects the colon or rectum. "To create an endogenous type I IFN reporter, we chose the colorectal cancer cell line HCT116, which is highly efficient for CRISPR-based gene editing, and surveyed IFNα induction of canonical type I IFN target genes (IFIT1, IFIT2, IFIT3, IFI27, IRF7, OASL, RSAD2)." (PMID 38358346, 2024).
colorectal tumors (1 paper, 2023). "Furthermore, PHF8 mRNA levels negatively correlated with IFNG, TLR3, IFIH1, STAT1 and OASL expression, suggesting that PHF8 restrains adaptive immune responses in human colorectal tumors." (PMID 37454216, 2023).
dermatomyositis (1 paper, 2022). Dermatomyositis (DM) is a type of idiopathic inflammatory myopathy characterized by evocative skin lesions and symmetrical proximal muscle weakness. "RNA-Seq transcriptome comparison of polymyositis and dermatomyositis has shown dermatomyositis-specific increases in OASL, EPSTI1, and IFI27 within CD8 + T cells." (PMID 34997119, 2022).
Diabetic Foot Ulcers (1 paper, 2024). "In Diabetic Foot Ulcers (DFU), OASL showed a positive correlation with gamma delta T cells in DFU, whereas negatively correlated with activated mast cells in CLE." (PMID 38434138, 2024).
Flavivirus Infections (1 paper, 2020). Infections with viruses of the genus FLAVIVIRUS, family FLAVIVIRIDAE. "The 2′,5′-oligoadenylate synthase (OAS) and RNase L pathways have previously been shown to restrict flavivirus infection, yet in ZIKVPR-infected SH-SY5Y cells, we observed that OAS3 was downregulated, while OASL was notably upregulated." (PMID 32380717, 2020).
hepatitis C virus infection (1 paper, 2019). A viral infection caused by the hepatitis C virus. "In addition, previous epidemiological studies have revealed the associations of SNPs in the human OASL gene with altered susceptibility to West Nile and hepatitis C virus infections." (PMID 31382472, 2019).
infarct (1 paper, 2023). "Moreover, we found that the percentage of OASL+ microglia was significantly associated with cerebral infarct volume after ischemia, suggesting that OASL+ microglia may be a critical player of neuroinflammation after ischemic stroke." (PMID 37183260, 2023).
infiltrating bladder urothelial carcinoma (1 paper, 2022). An invasive transitional cell carcinoma that arises from the urinary bladder urothelium. "OASL was only reported in the Sanchez-Carbayo bladder 2 dataset and was 1.455 times higher in infiltrating bladder urothelial carcinoma than in the normal samples." (PMID 36162993, 2022).
interstitial lung disease (1 paper, 2022). A diverse group of lung diseases that affect the lung parenchyma. "Some studies have suggested that OASL and OAS2 are upregulated in PBMCs and skin tissue of SSc patients, and OAS family genes are also increased in CD31+/CD102+ lung microvascular endothelial cells from SSc patients with end-stage interstitial lung disease." (PMID 35183246, 2022).
ischemic stroke (1 paper, 2023). A stroke disorder caused by obstruction of blood flow to the brain, due to thrombotic (local blood clot formation) or embolic (due to a blood clot or other material traveling from another site) event. "We also identified OASL+ subcluster with upregulated interferon-response-related gene, which is associated with age-dependent deteriorated infarct growth after ischemic stroke." (PMID 37183260, 2023). "In this study, we identified 3 distinct ischemic stroke-associated microglia (ISAM) specifically marked with MKI67 (MG4), OASL (MG5), and CH25H (MG6), respectively." (PMID 37183260, 2023). "Our data reveal previously unrecognized roles of the newly defined CH25H+ and OASL+ microglia subclusters following ischemic stroke, with novel insights for precise microglia modulation towards stroke therapy." (PMID 37183260, 2023). "In our study, we found that the proportion of interferon-related OASL+ microglia was considerably increased in aged mice compared to adult mice after ischemic stroke." (PMID 37183260, 2023). "We identified a relatively homeostatic subcluster with enhanced antigen processing and three “ischemic stroke associated microglia” (ISAM): MKI67+, CH25H+ and OASL+ subclusters." (PMID 37183260, 2023). "In addition, using systemic in vivo DNA labeling with 5-ethynyl-2′-deoxyuridine (EdU), we found EdU were incorporated in OASL+ MG5 and CH25H+ MG6 subclusters in the ischemic stroke brain 3 days after stroke." (PMID 37183260, 2023).
neuroblastoma (1 paper, 2023). Neuroblastoma (NB) is the most common solid, extracranial childhood tumor. "Here, we describe the protein expression levels of OAS1, OAS2, OAS3, and OASL in cells forming the NVU, such as primary human brain pericytes, astrocytes, EC, immortalized human microglial cells, and SH-SY5Y neuroblastoma cell line." (PMID 37209263, 2023). "Our studies also revealed a prominent expression of OAS2, OAS3, and OASL in SH-SY5Y cells; however, this is an immortalized neuroblastoma cell line, which does not fully represent mature neurons." (PMID 37209263, 2023).
Newcastle disease (1 paper, 2025). A condition caused by infection by the Newcastle disease virus, which may be characterized by conjunctivitis, respiratory illness, and diarrhea. "Studies on chickens exposed to the Newcastle virus demonstrated that targeting OASL holds promise for preventing and treating Newcastle disease in poultry." (PMID 41042757, 2025).
Stroke (1 paper, 2023). Sudden impairment of blood flow to a part of the brain due to occlusion or rupture of an artery to the brain. "Collectively, our findings identified MKI67+ microglia as the proliferative, CH25H+ as the neuroprotective, while OASL+ as the proinflammatory microglia subcluster which was associated with ischemic brain injury 3 days after stroke." (PMID 37183260, 2023). "Meanwhile, the OASL+ subcluster accumulated in the ischemic brain and was associated with the evolving of neuroinflammation after stroke, which was further aggravated in the aged mice brain." (PMID 37183260, 2023).
type 1 diabetes (1 paper, 2021). "OASL expression was decreased by 23% (p = 2.40 × 10−2, 95% CI −0.06, −0.08) in individuals with new-onset type 1 diabetes." (PMID 33973017, 2021).
type 2 diabetes (1 paper, 2021). "OASL was downregulated and has shown effects on C-reactive protein, γ glutamyltransferase and LDL-cholesterol, which are all related to cardiovascular events that are frequent in individuals with type 2 diabetes as well as inflammation." (PMID 33973017, 2021).